SOCS1 (suppressor of cytokine signaling 1)
Diseases named in the same sentence as SOCS1 in open-access papers (continued):
Sharing a sentence is not in itself a finding about the gene and the disease.
Autoimmunity (continued). "In this review, we highlight the importance of SOCS1 as a regulator of immune responses contributing to autoimmunity/autoinflammation and cancer and the potential use of SOCS1 mimetic peptide or gene therapy as treatment tactic." (PMID 31105556, 2019). "There is strong evidence that miR-155-mediated suppression of SOCS1 has biological significance in infection and autoimmunity." (PMID 28552958, 2017). "Evidently, SOCS1 protects keratinocytes of SLE patients from autoimmunity induced by uncontrolled IFN-γ signaling." (PMID 29085365, 2017). "T and NK cells from Socs1 knockout mice produce more IFNγ and show resistance to Th17 dependent autoimmunity due to reduced Th17 cell differentiation." (PMID 26203907, 2015). "We suggest that an important molecule, SOCS1, prevents acceleration of Treg plasticity and development of autoimmunity." (PMID 25133199, 2014). "Therefore, SOCS1 has crucial implications for maintaining immune homeostasis, especially under pathological conditions like autoimmunity." (PMID 38397811, 2024). "The vital role of vitamin D and microbiota in immune responses, including autoimmunity, SOCS1, and SOCS3, have been reported to be involved in Vitamin D metabolism through the VDR-miRNA155-SOCS1 pathway, negatively regulating inflammation and disease pathogenesis." (PMID 38006062, 2023). "In contrast, T cell-specific SOCS1 knockout mice were resistant to experimental autoimmune encephalomyelitis (EAE) in this case a result of enhanced IFNγ/STAT1-mediated suppression of Th17 cells that drive this model of autoimmunity." (PMID 34604264, 2021). "Several mechanisms can be proposed to explain autoimmunity in the context of SOCS1 insufficiency." (PMID 33087723, 2020). "Hence, given the widespread expression of SOCS1 and the cytokines’ orchestrating role in the immune system, several cell types probably contribute to autoimmunity in the context of SOCS1 haploinsufficiency." (PMID 33087723, 2020). "Similarly, heightened Stat1 activation in Tregs subjected to a selective ablation of SOCS1, a key negative regulator of Stat1 phosphorylation downstream of the IFN-γ receptor, was associated with analogous Th1-mediated pathology-associated autoimmunity." (PMID 31273052, 2019). "Thus, SOCS1 inhibition contributes to the autoimmunity in the progression of NPSLE by affecting the production of inflammatory cytokines and chemokines, activation of microglia, macrophages and astrocytes, and infiltration of immune cells." (PMID 29085365, 2017). "In this review, we describe the mechanism of SOCS1 action, focusing on the role of SOCS1 in autoimmunity and cancer, and discuss the potential for new SOCS1-directed cancer therapies that could be used to enhance adoptive immunotherapy and immune checkpoint blockade." (PMID 38947335, 2024). "In addition, SOCS1 deficiencies have been implicated within lupus, scleritis, multiple sclerosis, and asthma patients indicating that strategies that restore SOCS1 function may have efficacy in autoimmunity/autoinflammation." (PMID 35505065, 2022). "Also, it is reported that increasing SOCS1 expression by cells may be useful as a strategy to block CD8(+) T cell-mediated autoimmunity and to more generally prevent cytokine-dependent tissue destruction in inflammatory diseases." (PMID 25986394, 2015). "Consequently, increased SOCS1 expression in T cells might be unfavorable in relation to autoimmunity as a result of an increased Th17 inflammatory profile." (PMID 26203907, 2015). "Two immune-regulatory genes of potential interest for autoimmunity i.e., the major histocompatibility complex (MHC) class II transactivator (CIITA) gene and the suppressor of cytokine signaling 1 (SOCS1) gene, are located close to CLEC16A." (PMID 33795715, 2021). "The induction of the SOCS proteins by IFN-α is dependent on the TAM receptors and both SOCS1-/- and TAM receptor triple-knockout mice develop spontaneous lupus-like autoimmunity." (PMID 19624844, 2009).
Autoimmunity (continued). "SOCS1 and CIITA are recognized contributors to inflammation and autoimmunity." (PMID 38022642, 2023). "SOCS1−/− mice showed altered natural killer T (NKT) cells, with a decrease in invariant NKT cells but an increased activation of conventional NKT cells that supplemented the inflammation and autoimmunity observed in these mice." (PMID 34604264, 2021). "Overall, the presentation of human SOCS1+/- appears to be predominantly autoimmunity as opposed to infection." (PMID 34421895, 2021). "Together, these data show that SOCS1-KIR treatment reduced auto-reactive lymphocyte effector functions and suggest that therapeutic targeting of the SOCS1 pathway through peptide administration may have efficacy in mitigating autoimmune pathologies." (PMID 33737712, 2021). "In the absence of SOCS1, this deregulated proliferation results in impaired deletion of auto-reactive CD8+ T cells and increased potential for autoimmunity." (PMID 27583437, 2016).
Sepsis (32 papers, 2007 to 2026). Sepsis is defined as life-threatening organ dysfunction caused by a dysregulated host response to infection. "Prior scRNA‐seq findings revealed significant upregulation of ZBP1, XAF1, IFI44L and SOCS1 in B cells from sepsis patients that exhibit increased susceptibility to PANoptosis." (PMID 40600354, 2026). "For example, it has been established that SOCS1 suppresses TLRs and cytokine receptors and regulates metabolic reprogramming in DCs to protect different organs from damages caused by dysregulated inflammatory response during sepsis." (PMID 30086151, 2018). "Prior scRNA‐seq data showed pronounced upregulation of ZBP1, XAF1, IFI44L and SOCS1 in B cells from sepsis patients that displayed heightened PANoptosis sensitivity." (PMID 40600354, 2026). "Third, FTO O-GlcNAcylation promotes TRIM21-mediated FTO ubiquitination degradation, which induces Socs1 m6A methylation and sustains SOCS1 induction to maintain the negative feedback control of macrophage inflammatory cytokine storm in sepsis." (PMID 40642069, 2025). "In contrast, the inhibition of miR-155 attenuates sepsis-induced liver injury by enhancing the expression of suppressor of cytokine signaling 1 (SOCS1) and blocking the JAK/STAT pathway." (PMID 40041174, 2025). "This miRNA promotes the formation of M1 macrophages and induces robust cytokines production by targeting SHIP1 and SOCS1 during sepsis-related acute lung injury." (PMID 39744123, 2024). "We have also shown that SOCS-1 inhibits glycolysis and inhibits inflammatory responses during sepsis." (PMID 33690673, 2021). "For instance, miR‐30a suppresses proliferation and increases apoptosis of hepatocytes by regulating SOCS‐1‐mediated JAK/STAT pathway in sepsis rats, and MCPIP1‐regulated miR‐9/SIRT1 axis is involved in LPS‐induced liver injury." (PMID 32369227, 2020). "For example, miR‐30a inhibits proliferation and promotes apoptosis of hepatocytes via targeting SOCS‐1 in sepsis rats and MCPIP1‐controlled miR‐9 is involved in septic liver injury by regulating SIRT1 expression." (PMID 32369227, 2020). "Chances for the induction of IFN-β and SOCS-1 were found equal in the late phase of the dynamics of the BRN associated with sepsis and due to this in late phase dynamics of sepsis, there are fewer chances for activation of PICyts to higher levels." (PMID 25255432, 2014). "The expression of MyD88 is inhibited by SOCS-1 and we observed that, in our sepsis-induced ALI model, the alveolar macrophages from diabetic animals over-expressed SOCS-1 mRNA." (PMID 23024779, 2012). "The results presented suggest that during sepsis AMs from diabetic rats over-express SOCS-1 which inhibits the expression of MyD88, thus preventing TLR-mediated signal transduction, NFkB activation and therefore the transcription of inflammatory genes." (PMID 23024779, 2012). "SOCS1 is also known to regulate the uptake of LPS in mouse hepatocytes, preventing sepsis." (PMID 39414916, 2024). "Suppressing SOCS1 may promotes glycolysis and pro-inflammatory responses in sepsis murine bone marrow cells via the STAT3/HIF-1α axis This implies that EV-miRNA may promote the glycolysis of septic macrophages." (PMID 39744123, 2024). "Furthermore, down-regulation of miR-208-5p impedes the NF-κB/HIF-1 pathway by initiating SOCS1, thereby lessening sepsis-elicited inflammatory stimulation and myocardial damage." (PMID 35599576, 2022). "Downregulation of Socs1 in rat hepatocytes activates Jak2-Stat3 in an animal model of sepsis." (PMID 36505769, 2022). "miR-155 can target and inhibit the expression of SHIP1 and SOCS1; thus, it may promote the inflammatory response of sepsis." (PMID 33505221, 2021). "Furthermore, RGS1, CCL3, and SOCS1 were connected to sepsis in animal studies, while for CTSD increased expression levels were observed in mice with induced septic shock." (PMID 25814982, 2015).
Sepsis (continued). "The inhibitory role of IFN-β was observed during the initial stages of dynamics, but it is tempting to speculate that SOCS-1 possibly inhibit the role of IFN-β during sepsis but has the ability to manage the hyperinflammatory condition." (PMID 25255432, 2014). "It is known that LPS induces NFκB activation in a MyD88-dependent manner during sepsis and that the expression of this adaptor protein is negatively regulated by SOCS-1 so we then investigated the MyD88 and SOCS-1 (Suppressor of Cytokine Signalling) expression in the septic animals." (PMID 23024779, 2012). "Thus in AMs from diabetic rats with sepsis, the enhanced expression of the molecular brake SOCS-1 decreases MyD88 expression and therefore NFκB activation does not occur." (PMID 23024779, 2012). "State graphs produced in non-septic signalling were found different from signalling during sepsis in terms of recurring signalling and activation of IFN-β and SOCS-1 in the late phase, which may reflect the immunosuppressive state of the septic patient in the later stages of sepsis." (PMID 25255432, 2014). "The results showed that p‐STAT1, SOCS1 and SOCS3 expression levels decreased after sepsis‐induced intestinal injury compared to the control group." (PMID 39844345, 2025). "Previously, we have utilized a SOCS-1 KIR blocking peptide termed iKIR that enhanced STAT-1 and STAT-3 phosphorylation in macrophages to promote cytokine storm during sepsis." (PMID 33690673, 2021). "In the future, we will perform in vitro experiments to further investigate our predictions and produce explicit insights into the diagnosis and treatment of sepsis by involving IFN-β and SOCS-1." (PMID 25255432, 2014). "In the first stage, IFN-β regulates the levels of PICyts before the induction of SOCS-1, whereas in second stage IFN-β can be induced and downregulate PICyts in late phases of sepsis." (PMID 25255432, 2014). "LPS treatment induces suppressor of cytokine signaling (Socs) 1 m6A methylation and sustains SOCS1 induction by decreasing Fto mRNA expression, which maintains the negative feedback control of macrophage cytokine storm in sepsis." (PMID 40642069, 2025). "Indeed, serum exosome-derived miR-155 from sepsis mice promote macrophage proliferation and production of proinflammatory cytokines by targeting SHIP1 and SOCS1." (PMID 33505221, 2021). "Moreover, the expression pattern of negative regulators such as SOCS-1 and IFN-β can be detrimental in case of sepsis." (PMID 25255432, 2014). "Unlike signalling in sepsis without any interventions, SOCS-1 did not play its part in late phase signalling dynamics." (PMID 25255432, 2014). "Intervention in SOCS-1 mediated downregulation of PICyts during non-septic signalling is discussed as CASE 1-N whereas in case of sepsis, it is discussed as CASE 1-S." (PMID 25255432, 2014). "This may suggest that therapeutic strategies during the course of sepsis should be devised according to the immune responses and expression levels of SOCS-1 and IFN-β as discussed in other studies for their role in sepsis." (PMID 25255432, 2014). "It was found that AMs from diabetic rats with sepsis express higher levels of SOCS1 mRNA compared with non-diabetics." (PMID 23024779, 2012). "Additionally, ZBP1, XAF1, IFI44L, SOCS1, and PARP14 were notably high in HighPANscore cells, aligning with our observations of upregulated expression of IFI44, IFIH1, IFIT1, IFIT2, and RSAD2 in lung tissues from sepsis-induced animal models." (PMID 38239341, 2023). "Notably, the analysis identified potential mediators of sepsis-induced immunosuppression, including Arg-1, SOCS-1, and SOCS-3, which were highly upregulated in multiple cell types and negative costimulatory molecules, including PD-1 and CTLA-4 upregulated in sepsis." (PMID 37317092, 2023).
Sepsis (continued). "The boxplot revealed 26 differentially expressed genes between the sepsis-induced ALI and control samples: Ncf2, Slc2a6, Cd44, Txnip, Slc2a1, Ubc, Hspb1, Zfp36, Arntl, Ddit4, Tnfaip3, Txnrd1, Mt1, Hmox1, Gch1, Gclc, Stat3, Egfr, Hif1a, Bach1, Socs1, Dusp1, Cdkn1a, Fth1, Steap3, and Alox12." (PMID 37081490, 2023). "However, these predictions need to be further validated using wet laboratory experimental studies to further explore the roles of inhibitors such as SOCS-1 and IFN-β, which may alter the levels of proinflammatory cytokines at different stages of sepsis." (PMID 25255432, 2014). "In normal infections, the pattern of IFN-β and SOCS-1 is sequential, whereas in case of sepsis, this sequential pattern of IFN-β and SOCS-1 may be changed and system becomes more vulnerable towards higher levels of pathogen load due to compromised levels of PICyts." (PMID 25255432, 2014). "SOCS-1 and CIS expression were increased 4 hours following induction of sepsis, but by 24 hours were no different from measurements in sham-operated animals – whereas SOCS-3 expression remained elevated at 24 hours." (PMID 17634149, 2007).
colitis (27 papers, 2013 to 2025). Inflammation of the colon. "SOCS1+/− mice and those with T cell-specific SOCS1 ablation were more susceptible to experimentally-induced colitis due to enhanced IFNγ/STAT1-mediated suppression of Treg cells." (PMID 34604264, 2021). "Dextran sulfate sodium-induced colitis has been induced in transgenic mice expressing a point mutation in SOCS-1 (SOCS-1-F59D), which inhibits the activity of SOCS family proteins." (PMID 29534522, 2018). "Although Rag gene deficient mice are free of spontaneous colitis, SOCS1−/−Rag2−/− mice develop severe colitis." (PMID 24391643, 2013). "Luteolin-7-glucopyranoside exhibits antioxidant and anti-inflammatory properties by modulating the JAK1/STAT6/SOCS1 pathway and alleviating inflammatory diseases, such as colitis." (PMID 40283142, 2025). "The circRNA/miRNA/mRNA competitive endogenous RNA (ceRNA) network analysis showed that the candidate miRNAs were connected to well-known colitis-associated CRC ACVR2A, SOCS1, IGF2BP1, FAM126A, and CCDC85C mRNAs, and circ-SHPRH circRNA." (PMID 38891888, 2024). "On the one hand, the RT-qPCR of colonic tissues was executed to verify the transcript levels of the filtered genes, and SOCS1 was found to be elevated to the greatest degree of the UTI group compared with that of the colitis group." (PMID 38397811, 2024). "Of note, Bst2, Socs1, and Usp18 showed significant induction in B. fragilis–monocolonized mice compared with GF mice during experimental colitis." (PMID 38085267, 2024). "Berberine has been found to play a regulatory role in macrophage M1 polarization in DSS-induced colitis through the AKT1-suppressor of cytokine signaling-1 (SOCS1)-NF-κB signaling pathway." (PMID 34149863, 2021). "T cell-specific SOCS1-deficient mice developed autoimmune inflammatory diseases with age, and were very sensitive to dextran sulfate sodium (DSS)-induced colitis and ConA-induced hepatitis." (PMID 28146070, 2017). "Increased miR-155 in patients with colitis was shown to decrease suppressor of cytokine signaling 1 (SOCS1) expression via targeting its 3'UTR." (PMID 26610589, 2015). "Therefore, among all the molecular targets of our miRNA candidates, POU2F1, SOCS1, and circ-SHPRH are better characterized for their involvement in colitis-associated CRC." (PMID 38891888, 2024). "Given the phosphorylation inhibition function of SOCS1, we speculated that UTI regulates the JAK2/STAT3/SOCS1 axis to reduce an inflammatory response and barrier impairment in colitis." (PMID 38397811, 2024). "Moreover, SOCS1-deficient mice exhibited dysregulated IL-4 and IFN-γ secretion in a rodent colitis model." (PMID 36558966, 2022). "EHLJ7 may induce intestinal flora to overexpress SCFA, especially butyric acid and then inhibit colitis inflammation through inhibition of JAK2/STAT3/SOCS1 pathway." (PMID 32038241, 2019). "SOCS1 may either promote or suppress tumorigenesis: Tumor suppressive activity of SOCS1 was observed in SOCS1-/- knockout mice, which develop colitis-induced colon tumors." (PMID 24058673, 2013). "However, the adoptive transfer of IL10-producing-Tregs is sufficient to prevent colitis in SOCS1−/−Rag2−/− mice, again underscoring the interconnected nature of SOCS1 signaling and regulatory Tregs in the regulation of immune responses." (PMID 24391643, 2013). "SOCS1-heterozygous mice have increased Th1 differentiation and are susceptible to dextran sodium sulfate-induced colitis.94) In order to elucidate the function of SOCS1 in T cells, conditional knockout (cKO) mice lacking SOCS1 specifically in T cells were generated." (PMID 34121041, 2021).
colitis (continued). "In the absence of SOCS1, Tregs become harmful effector T cells that may induce severe colitis, liver degeneration, or lymphoid deficiencies." (PMID 28146070, 2017). "Though BBR’s efficacy on colitis has been verified in plentiful ways, for instance, BBR represses macrophage M1 polarization via the AKT1/SOCS1/NF-κB pathway for prevention of dextran sodium sulfate (DSS) -stimulated colitis." (PMID 35259053, 2022). "The top 3 predicted upstream regulators in inactive extensive colitis were miR-155-5p, SOCS1, and TREM1, regulating CXCL2 and SOCS1; CXCL2 and SOCS1; and CXCL2, HES4, and TIFA, respectively." (PMID 32731480, 2020). "DSS‐induced colitis was reduced in STAT1 knockout mice whereas mice with haploinsufficiency of SOCS1, a negative regulator of STAT1, showed more severe colitis." (PMID 29419930, 2018). "Studies of experimental colitis in rodents have shown that SOCS1 and SOCS3 levels are increased during inflammation and that both the heterozygous state and ablation of SOCS1 induces more severe intestinal inflammation." (PMID 28486400, 2017). "Our study demonstrated correlations between miR-155, SOCS1, and STAT3 in the ascending colon of PSC patients, with or without concurrent colitis, and in the sigmoid colon of UC patients." (PMID 35563301, 2022). "Previous work has demonstrated that SOCS-1 plays an important role in preventing murine colitis by restricting the cytokine signals, however, whether the effect of curcumin on anti-inflammation in TNBS-induced IBD is mediated by SOCS-1 has not been clarified." (PMID 27544348, 2016).